SIRT2 (sirtuin 2)
Diseases named in the same sentence as SIRT2 in open-access papers (continued):
Sharing a sentence is not in itself a finding about the gene and the disease.
rhabdomyosarcoma (2 papers, 2014 to 2021). A rare aggressive malignant mesenchymal neoplasm arising from skeletal muscle. "Using siRNA to knock down SIRT1 and SIRT2, we show that the expression of both proteins is crucial for the survival of rhabdomyosarcoma cells and that the loss of SIRT1 expression results in a decreased LC3II expression." (PMID 25341037, 2014). "Our results show that SIRT1 and SIRT2 expressions are crucial for the survival of synovial sarcomas and rhabdomyosarcomas, and demonstrate that the pharmacological inhibition of sirtuins impairs the autophagy process and induces tumor cell death." (PMID 25341037, 2014). "SIRT1 and SIRT2 mRNA expressions in the rhabdomyosarcoma cell lines RD, RH30 and RMS were the lowest among the samples examined." (PMID 25341037, 2014). "In the present paper, we have investigated the expression and activity of SIRT1 and SIRT2 in synovial sarcomas and rhabdomyosarcomas, and we evaluated the effects of sirtuin modulation with the small-molecule tenovin-6 and with SIRT1 and SIRT2 siRNA." (PMID 25341037, 2014). "In conclusion, our study demonstrates that SIRT1 and SIRT2 expression and activity are crucial for the survival of synovial sarcomas and rhabdomyosarcomas, and that SIRT1 and SIRT2 inhibition impairs the autophagy process inducing cell death." (PMID 25341037, 2014).
rheumatoid arthritis (2 papers, 2020 to 2021). A chronic, systemic autoimmune disorder characterized by inflammation in the synovial membranes and articular surfaces. "Remarkably, expression levels of SIRT2 mRNA were dramatically decreased in extracellular plasma of rheumatoid arthritis patients compared with healthy controls." (PMID 33803627, 2021). "Remarkably, expression level of SIRT2 mRNA was dramatically decreased in extracellular plasma of rheumatoid arthritis patients compared with the healthy controls." (PMID 32515550, 2020). "More recently, SIRT2 mRNA expression levels of extracellular plasma was found to be reduced in 54 rheumatoid arthritis patients compared with healthy controls." (PMID 32515550, 2020).
schizophrenia (2 papers, 2022 to 2024). A major psychotic disorder characterized by abnormalities in the perception or expression of reality. "Sirtuin 2 (SIRT2) has been implicated in schizophrenia, particularly through its role in oligodendrocyte development and myelination." (PMID 39404407, 2024). "Pharmacological inhibition of SIRT2 in mice led to behavioral deficits and myelination abnormalities reminiscent of schizophrenia." (PMID 39404407, 2024).
schwannoma (2 papers, 2013 to 2018). A benign, usually encapsulated slow growing tumor composed of Schwann cells. "We speculate that SIRT2 pharmacological inhibition may have some therapeutic value for NF2-associated schwannomas by promoting necrosis." (PMID 24259290, 2013). "In order to validate the results in our cellular model, we measured SIRT2 and acetyl-α-tubulin levels in a human NF2 cell line created by immortalization of schwannoma cells from a NF2 patient with the E6 and E7 genes of the papillomavirus." (PMID 24259290, 2013). "Hence, there may be value to SIRT2 and SIRT1 combinatorial inhibition in schwannoma treatment." (PMID 24259290, 2013).
serous ovarian carcinoma (2 papers, 2019 to 2022). "SIRT2 predicted poor survival when upregulated in patients with OC, while reduced expression of SIRT2 was observed in 13 samples of serous ovarian carcinoma compared with 11 samples of normal ovarian surface epithelial tissues." (PMID 31572453, 2019). "The expression of SIRT2 is decreased in serous ovarian cancer, and down-regulation of SIRT2 promotes the expression of cyclin-dependent kinase 4 (CDK4), thereby promoting the proliferation, migration and invasion of serous ovarian cancer cells in vitro." (PMID 36505774, 2022).
Spastic paraplegia (2 papers, 2017 to 2020). Complete loss of the ability to move the lower limbs accompanied by spasticity of the lower limbs. "This is supported by two other studies in which SIRT2 was reduced, both in a model of spastic paraplegia SPG2 and in a model of long‐term vitamin E‐deficient mice." (PMID 28984064, 2017).
staphylococcus aureus infection (2 papers, 2018 to 2023). An infectious process in which the bacteria Staphylococcus aureus is present. "Similarly, in chronic Staphylococcus aureus infection in mice, the survival rate was increased with SIRT2 deficiency, and in an SIRT2−/− murine model, bacterial infections were reduced." (PMID 36719240, 2023). "Further, SIRT2 deficient mice show increased survival during Staphylococcus infection." (PMID 30452468, 2018).
synovial sarcoma (2 papers, 2014 to 2021). "We quantified SIRT1 and SIRT2 mRNA expression in 12 fresh frozen synovial sarcomas (SS), 7 sarcoma cell lines and 4 primary human mesenchymal cells (diploid fibroblasts and mesenchymal stem cells) using QRT-PCR." (PMID 25341037, 2014).
tuberculosis (2 papers, 2015 to 2020). A chronic, recurrent infection caused by the bacterium Mycobacterium tuberculosis. "Although absence of Sirt2 clearly impaired L. monocytogenes infection, little is known on its impact in infections by other intracellular pathogens, such as Mycobacterium tuberculosis, the causative agent of tuberculosis." (PMID 26135889, 2015). "For instance, genes involved in antigen presentation, Th17 cell differentiation, cytokine-cytokine receptor interaction, NF-κB signaling, tuberculosis, etc were significantly upregulated while PI3K/Akt signaling pathway was downregulated in SIRT2 inhibited samples." (PMID 32697192, 2020).
amoebiasis (1 paper, 2018). "No large β8-β9 insertions have been detected in SIRT2 proteins of other protozoan parasites, including Entamoeba histolytica, the causative agent of amoebiasis, Toxoplasma gondii, (toxoplasmosis) and the malarial agent Plasmodium falciparum." (PMID 29543820, 2018).
B-cell lymphomas (1 paper, 2020). "In vitro SIRT2 inhibitory activity (IC50) and cytotoxicity (LC50) of SIRT2 inhibitors in B-cell lymphoma and other cancer cell lines." (PMID 31973227, 2020). "In particular, compounds 55 (IC50 SIRT2 0.25 μM and <25% inhibition at 50 μM against SIRT1 and SIRT3) and 56 (IC50 SIRT2 0.78 μM and <25% inhibition at 50 μM against SIRT1 and SIRT3) showed apoptotic as well as strong anti-proliferative properties against B-cell lymphoma cells." (PMID 31973227, 2020).
bacterial sepsis (1 paper, 2017). "Therefore, we compared the impact of SIRT2 deficiency during rapidly lethal, sub-lethal, and chronic bacterial infections induced by E. coli, K. pneumonia, and S. aureus, three of the most frequent causes of bacterial sepsis in humans." (PMID 28894448, 2017).
brain tumor (1 paper, 2025). "Collectively, these findings highlight SIRT2 as a critical molecular target in SMARCB1-deleted ATRT, indicating that therapeutic strategies aimed at SIRT2 inhibition may offer a novel approach for treating this highly aggressive pediatric brain tumor." (PMID 40710366, 2025).
breast adenocarcinoma (1 paper, 2023). "SIRT2 knockdown or inhibition induces degradation of c-Myc protein in tumor cells by inducing its ubiquitination, and treatment with FLS-359 for 72 hours dramatically reduced the level of the oncoprotein in MDA-MB-231 breast adenocarcinoma cells." (PMID 37317966, 2023).
brucellosis (1 paper, 2025). Brucellosis is a bacterial infection that spreads from animals to people via unpasteurized dairy products or by exposure to contaminated animal products or infected animals. "In conclusion, this study not only reveals the role of SIRT2 in regulating cell apoptosis during Brucella infection but also provides new directions for the development of targeted therapies against brucellosis." (PMID 40317067, 2025).
calcification (1 paper, 2025). Process by which organic tissue becomes hardened by the physiologic deposit of calcium salts. "Notably, SIRT1, SIRT2, SIRT3, SIRT6, and SIRT7 have demonstrated therapeutic potential in the treatment of vascular calcification." (PMID 41480421, 2025).
Candida infection (1 paper, 2017). "Candidiasis was induced by i.v. inoculation of 105 CFU/ml C. albicans into SIRT2+/+ and SIRT2−/− mice (n = 14 and 16)." (PMID 28894448, 2017). "Mice died 9–40 days postinfection, without survival differences between the SIRT2+/+ and SIRT2−/− groups (71 vs 56%; P = 0.4), suggesting that SIRT2 deficiency did not compromise host defenses to Candida infection." (PMID 28894448, 2017).
cerebral cysts (1 paper, 2023). "In our study, the expression of SIRT2 was up-regulated after chronic infection, which is consistent with Mcconkey’s report, they found that dopaminergic cells and brain tissues encysted with cerebral cysts have increased levels of dopamine synthesis and release." (PMID 37721957, 2023).
Charcot-Marie-Tooth disease (1 paper, 2025). An inherited degenerative disorder involving the peripheral nerves. "In Charcot-Marie-Tooth disease (CMT), a hereditary peripheral neuropathy, mutant glycyl-tRNA synthetase (GARS) loses its binding capacity to SIRT2, leading to reduced α-tubulin acetylation levels." (PMID 41356121, 2025).
chordoma (1 paper, 2023). Chordomas are rare malignant tumors arising from embryonic remnants of the notochord in axial skeleton. "Genes central for module 2 (and thus probably important for functioning of chordomas in both clusters) were either responsible for cell division and DNA repair process (e.g. ATM, CHEK, BMI1, MDM2) or parts of inhibitors of apoptosis cascade (e.g. CASP2, CASP8, SIRT2)." (PMID 37434245, 2023).
chronic hepatitis B (1 paper, 2025). "AGK2 suppresses HBV replication through direct antiviral actions, and by epigenetic modulation of cccDNA, indicating that using AGK2 to target SIRT2 and associated epigenetic regulators shows promise as a functional cure for chronic hepatitis B." (PMID 40270769, 2025).
chronic pancreatitis (1 paper, 2018). A chronic inflammatory process causing damage and fibrosis of the pancreatic parenchyma. "The results of these in vivo experiments suggest that loss of Sirt2 prolonged the whole body inflammatory response by caerulein-induced acute and chronic pancreatitis." (PMID 30405152, 2018).
colorectal neoplasm (1 paper, 2022). A benign or malignant neoplasm that affects the colon or rectum. "To explore the molecular basis of colorectal tumorigenesis specifically, we generated an interaction network with the proteins functioning in colorectal neoplasms among SIRT2 direct hits." (PMID 35264593, 2022).
delirium (1 paper, 2025). A disorder characterized by confusion; inattentiveness; disorientation; illusions; hallucinations; agitation; and in some instances autonomic nervous system overactivity. "Sirtuins could alleviate surgery‐induced mitochondrial dysfunction and delirium‐like behavior by modulating mtDNA methyltransferase activity, and we hypothesized that fluctuations in SIRT2 influence susceptibility to delirium‐like behavior in T2DM rats." (PMID 40104261, 2025). "This study found that SIRT2 levels were closely associated with delirium‐like behavior." (PMID 40104261, 2025). "The reduction of SIRT2 following orthopedic surgery in the hippocampus of T2DM rats inhibits the acetylation process of PGC‐1α and the subsequent mitochondrial biogenesis process, leading to mitochondrial dysfunction and postoperative delirium‐like behavior." (PMID 40104261, 2025). "Instead of affecting total PGC‐1α expression, the absence of SIRT2 may prevent acetylated PGC‐1α from entering the nucleus, thereby hindering the activation of mitochondrial biogenic pathways and leading to mitochondrial dysfunction and delirium‐like behavior in T2DM rats." (PMID 40104261, 2025).
diabetic angiopathy (1 paper, 2025). "In SIRT2-mediated NLRP3 deacetylation, 1,8-cineole is essential for anti-pyroptotic and anti-inflammatory processes with diabetic angiopathy." (PMID 41567643, 2025).
dilated cardiomyopathy (1 paper, 2023). Cardiomyopathy which is characterized by dilation and contractile dysfunction of the left and right ventricles. "Additionally, we noted a significant increase in the levels of SIRT2 in the explanted hearts from end-stage HF patients with dilated cardiomyopathy." (PMID 37728319, 2023). "(B) SIRT2 in human hearts from healthy patients and patients with dilated cardiomyopathy." (PMID 37728319, 2023).
endometrioid adenocarcinoma (1 paper, 2019). An adenocarcinoma characterized by the presence of malignant glandular epithelial cells resembling endometrial cells. "SIRT2 expression was lower in serous and endometrioid adenocarcinoma in Lu’s dataset, whereas SIRT5 was upregulated in those types of OC in Hendrix’s dataset compared with normal tissues." (PMID 31572453, 2019).
esophageal adenocarcinoma (1 paper, 2014). A malignant tumor with glandular differentiation arising predominantly from Barrett mucosa in the lower third of the esophagus. "A panel of three proteins (EGFR, TRIM44, and SIRT2) had been shown to determine prognosis for esophageal adenocarcinoma (EAC), and a combination of this panel and clinicopathologic features could stratify patients into subgroups with different prognosis." (PMID 25337715, 2014).
gastroesophageal junctional adenocarcinoma (1 paper, 2017). "Additionally, aberrant SIRT2 expression was reported to predict poor survival outcome of esophageal and gastroesophageal junctional adenocarcinoma patients." (PMID 28061480, 2017).
HCMV infection (1 paper, 2023). "Using a combination of Western blotting and targeted mass spectrometry, we analyzed the impact of AGK2 treatment on SIRT2 protein abundance throughout HCMV infection." (PMID 37916830, 2023). "To pinpoint which proteins belonging to these processes SIRT2 regulates during HCMV infection, we sought to characterize its deacetylase activity substrates." (PMID 37916830, 2023). "We propose that SIRT2 normally functions to inhibit cell cycle progression from G1 to S phase during HCMV infection, which promotes maintenance of cells in G1, the cell cycle stage that supports HCMV replication." (PMID 37916830, 2023). "To understand what drives this function, we characterized SIRT2 substrates and temporal changes in its protein interactions by performing acetylome and interactome analyses during HCMV infection." (PMID 37916830, 2023). "In studying the provirus effect of SIRT2 during HCMV infection, we have also identified and characterized an SIRT2-regulated acetylation site on CDK2." (PMID 37916830, 2023). "We found CDK2 to interact with SIRT2 in uninfected cells and at early time points of HCMV infection." (PMID 37916830, 2023). "SIRT2 is known to be multi-functional, being positioned to potentially regulate diverse cellular processes that are important during early stages of HCMV infection, including gene expression, cellular metabolism, cytoskeletal organization, and cell cycle progression." (PMID 37916830, 2023). "Given its multi-functionality and localization to compartments where we observe global alterations in acetylation during HCMV infection, SIRT2 deacetylase activity may be poised for both virus manipulation and host defense processes." (PMID 37916830, 2023). "In the context of HCMV infection, knockdown of SIRT2 resulted in elevated virus titers." (PMID 37916830, 2023). "Next, we investigated whether SIRT2 functions through the regulation of CDK2 activity during HCMV infection." (PMID 37916830, 2023). "Given that there is still limited information about the global effect of SIRT2 on the cellular acetylome, especially in a primary cell type, we investigated changes in the protein acetylome and proteome following AGK2 treatment and HCMV infection." (PMID 37916830, 2023).
hearing loss (1 paper, 2024). "SIRT1 (n = 29) and SIRT3 (n = 19) have been the most studied sirtuins, while SIRT2 (n = 1) and SIRT7 (n = 1) were rarely studied in connection to hearing loss." (PMID 39204103, 2024).
hemochromatosis (1 paper, 2018). A disorder of iron metabolism characterized by a triad of HEMOSIDEROSIS; LIVER CIRRHOSIS; and DIABETES MELLITUS. "Sirt2 KO hepatocytes are susceptible to iron deficiency and Sirt2 activity is negatively correlated with iron content in liver biopsies from human fatal neonatal hemochromatosis patients." (PMID 30364139, 2018).
Hypercholesterolemia (1 paper, 2023). An increased concentration of cholesterol in the blood. "Generally, lysophosphatidylcholine (LPC) and phosphatidylcholines (PC), downregulated in SIRT2 KO mice and enriched in the hepatoprotective choline metabolism and glycerophospholipid metabolism pathways, inhibit the progression of NAFLD via lipotropic action and alleviating hypercholesterolemia." (PMID 37240315, 2023).
hypothyroidism (1 paper, 2023). Abnormally low levels of thyroid hormone. "Kocaturka found that rats with hypothyroidism exhibited reduced levels of sirtuin 2 protein expression in the retinal ganglion cell layer." (PMID 37634057, 2023).
inflammatory bowel disease (1 paper, 2014). A spectrum of small and large bowel inflammatory diseases of unknown etiology. "Further investigations to identify therapies targeting SIRT2 to improve inflammatory bowel disease are hence warranted." (PMID 25072851, 2014). "This also leads us to speculate that the activation of SIRT2 may be a potential approach to treat inflammatory bowel disease." (PMID 25072851, 2014). "Finally, we speculate that the activation of SIRT2 may be a potential approach for the treatment of inflammatory bowel disease." (PMID 25072851, 2014).
invasive breast carcinoma (1 paper, 2022). A carcinoma that infiltrates the breast parenchyma. "The analysis of public genomic databases suggests that approximately 2.6% of invasive breast carcinoma and 1.73% of noninvasive BC samples show patterns of SIRT2 genetic alterations." (PMID 35406775, 2022).
ischemic cardiomyopathy (1 paper, 2023). Ischemic cardiomyopathy is a cardiomyopathy in which a weakness in the muscle of the heart due to inadequate oxygen delivery to the myocardium with coronary artery disease being the most common cause. "We also assessed the levels of SIRT2 in explanted hearts from patients with ischemic cardiomyopathy and showed that SIRT2 is increased in these hearts." (PMID 37728319, 2023).
joint diseases (1 paper, 2025). "Additionally, the impact of SIRT2 on other types of joint diseases remains unclear, and future clinical studies are required to assess its efficacy and safety." (PMID 40620356, 2025).
liver dysfunction (1 paper, 2023). "Combined with the results that serum alanine aminotransferase (ALT) and aspartate aminotransferase (AST) levels were significantly elevated in SIRT2 KO mice fed with HFCS compared to those of WT mice, these data collectively indicate an aggravated severity of liver dysfunction in SIRT2 KO mice." (PMID 37240315, 2023).
memory (1 paper, 2025). The activities involved in the mental information processing system that receives (registers), modifies, stores, and retrieves informational stimuli. "Taken together, we demonstrate the role of SIRT2 in aberrant GABA production from reactive astrocytes by genetically knocking it down and rescuing tonic GABA current as well as memory deficits." (PMID 39815261, 2025).
metastatic cancer (1 paper, 2017). A carcinoma which has spread from the original site of growth to another anatomic site. "Thus, an increase in nuclear P300 and decrease in SIRT2 was demonstrated during progression from benign to primary and metastatic cancer." (PMID 29262808, 2017).